LIF (LIF interleukin 6 family cytokine)
Diseases named in the same sentence as LIF in open-access papers (continued):
Sharing a sentence is not in itself a finding about the gene and the disease.
cancer (continued). "Systematic proteomic investigation of secreted disease mediators identified the leukemia inhibitory factor (LIF) as a key paracrine factor from CAFs for STAT3 activation in cancer cells of the epithelial compartment." (PMID 32752017, 2020). "In conclusion, LIF contributes to cancer progression by enhancing regional lymphatic spread, thereby leading to an advanced cancer stage." (PMID 31973037, 2020). "LIF has been reported to have distinct effects on tumorigenesis and metastatic spread in different cancers." (PMID 31973037, 2020). "Then expression of LIF and TGFβ is increased by cancer cell and they are imported to the fibroblast as input signals V1 and V2." (PMID 32384110, 2020). "Despite the similar sequence homology, structure, and intron-exon and promoter elements between OSM and LIF, the individual IL-6 cytokines have differing roles in cancer and bone biology." (PMID 32023849, 2020). "Another recently revealed paracrine factor involved in stroma–cancer cell interactions is leukemia inhibitory factor (LIF)." (PMID 32116785, 2020). "LIF can promote cancer cell progression, including migration and invasion, through INHBA in OSCC cells." (PMID 31973037, 2020). "As well, we identified several proinflammatory cytokines such as IL-1 alpha, IL4, IL6, LIF, TNF which have been implicated in cancer cachexia." (PMID 33334063, 2020). "Regulation of LIF downstream molecules such as INHBA inhibits the invasion or migration ability of cancer cells." (PMID 31973037, 2020). "The results of the present study revealed that almost half of the patients with stage 4 cancer had low LIF expression (17/39)." (PMID 31973037, 2020). "LIF overexpression enhanced INHBA expression to regulate cancer cell motility, whereas LIF knockdown reduced cell motility and INHBA expression in shLIF transfectants." (PMID 31973037, 2020). "Leukemia inhibitory factor (LIF) is a pleiotropic cytokine regulating cell differentiation, proliferation and survival in the embryo and the adult, and is also involved in cancer development." (PMID 32245422, 2020). "The αSMA‐positive myCAFs were located adjacent to the cancer duct structure and at distant places, whereas the LIF‐positive iCAFs were located mainly far from the cancer cells, as previously reported (upper left)." (PMID 32931156, 2020). "Here, the authors show that LIF expression is specifically induced by KRAS and constitutes a potential target to treat these KRAS-mutated cancers." (PMID 31296870, 2019). "Identifying non-STAT3 downstream effectors/signaling pathways specifically mediated by LIF can be beneficial for evaluating therapeutic efficiency of LIF blockade in KRAS mutant cancers." (PMID 31296870, 2019). "All these data clearly indicate that LIF/LIFr and related signaling pathways are crucial in cancer initiation, implantation, growth and diffusion, in a way that recalls their function in embryo development." (PMID 30899759, 2019). "Of note, fibroblasts and macrophages present in the cancer microenvironment secrete the cytokine Leukemia Inhibitory Factor (LIF), which can increase Schwann cells migration and neural plasticity leading to enhanced neurite outgrowth at least in vitro." (PMID 31248001, 2019). "Similar to cancer, many of these factors including TNFα, IL-6, IL-1, LIF, activin A, and myostatin activate Akt in skeletal muscle cells while stimulating muscle protein loss." (PMID 31480237, 2019). "The results of both our in vitro and in vivo studies clearly showed that LIF was predominantly expressed by fibroblastic cells rather than OSCC cells, but further analysis is required to clarify the expression profile of LIF in cancer tissues." (PMID 29444110, 2018). "Given the significant role of LIF/YAP1-focal adhesion signaling in cancer dissemination, targeting of this pathway presents a promising opportunity to block metastasis." (PMID 30504771, 2018).
cancer (continued). "Cellular LIF-high cancer cells (cLIF) exhibited fibroblastic morphology, leading to the suggestion that cytoplasmic LIF reprograms the cancer invasion mode." (PMID 30504771, 2018). "Mechanistically, cellular LIF appears to modulate the LIFR–YAP–focal adhesion axis to drive cancer invasion." (PMID 30504771, 2018). "Results of immunostaining revealed morphological changes from a flattened epithelioid appearance to spindle-like fibroblastic morphology in YAP1-depleted WT and LIF+/− cells, resembling that observed in cLIF cancer cells." (PMID 30504771, 2018). "cLIF cells were capable of creating larger holes in the HUVEC layer than WT cancer and LIF+/− cancer cells." (PMID 30504771, 2018). "In conclusion, we demonstrated that OSCC cells stimulated fibroblasts to produce LIF, and the fibroblast-derived LIF, in turn, mediated cancer-cell migration and invasion." (PMID 29444110, 2018). "Overexpression of LIF significantly enhances proliferation, growth, and metastasis of both cultured human cancer cells and xenografts." (PMID 29899555, 2018). "Improved understanding of the roles of LIF in cancer metastasis should facilitate the prevention of cancer dissemination through sequestering of its regulators or downstream effectors." (PMID 30504771, 2018). "Higher cytoplasmic LIF enhances cancer vascular dissemination and local invasion mechanistically through modulation of YAP1-FAK/PXN signaling." (PMID 30504771, 2018). "Conversely, our immunohistochemical staining for LIF revealed that LIF expression was considerably lower in cancer cells than in CAFs, and that in >50% of the cases, the cancer cells were LIF-negative." (PMID 29444110, 2018). "Both WT parental and LIF+/− cancer cells exhibited a collective migration pattern whereas cLIF cells displayed a mesenchymal migration mode." (PMID 30504771, 2018). "Chronic or repeated exposure of cancer cells with environmental LIF can lead to downregulation of LIFR." (PMID 30504771, 2018). "These intriguing data potentially support our results, but the precise role of LIF in the cancer microenvironment and its relation to fibroblasts remain incompletely elucidated, and should be further analyzed in future studies by using CAFs." (PMID 29444110, 2018). "Our findings collectively indicate that cytoplasmic LIF positively regulates focal adhesion dynamics to facilitate cancer invasion." (PMID 30504771, 2018). "Pharmaceutical intervention with AZD0530 markedly reverses LIF-mediated cancer dissemination and local invasion through promotion of cytoplasmic accumulation of YAP1 and suppression of focal adhesion kinases." (PMID 30504771, 2018). "On the other hand, many of the WT and LIF+/− cancer cells still exhibited a round-up morphology at 6 h, although they displayed spreading at 24 h post-plating indicative of a less efficient attachment mechanism in these cell groups." (PMID 30504771, 2018). "Collectively, our results suggest that OSCC stimulates fibroblasts to produce LIF, which, in turn, participates in cancer-cell invasion." (PMID 29444110, 2018). "Several recent studies have shown a correlation between LIF and human cancer metastasis but the mechanisms remain largely unclear." (PMID 30504771, 2018). "The negative correlation between reduced YAP1 expression and metastasis is supported by the observation that depletion of YAP1 in WT or LIF-low cancer cells resulted in a phenotype resembling LIF-rich cancer cells." (PMID 30504771, 2018). "Studies published during the early 1990s reported that LIF can be produced by cancer cells and induce cachexia." (PMID 28865476, 2017). "The pro-inflammatory cytokine LIF governs fibroblast activation in cancer by regulating the myosin light chain 2 activity." (PMID 27901489, 2017). "In cell culture, LIF from the C26 cells was entirely responsible for the atrophy effect of cancer cell conditioned medium on C2C12 myotubes." (PMID 28993738, 2017).
cancer (continued). "We recently showed that the cytokine LIF is completely responsible for myotube atrophy in a cell culture model of cancer cachexia." (PMID 28993738, 2017). "A mouse specific ELISA was used to measure LIF levels in myotube cultures containing added cancer cell CM and in myotube cultures incubated with Transwell® inserts containing cancer cells." (PMID 28993738, 2017). "It is possible that the induction of EMT by LIF can lead to the resistance towards therapy in cancer patients with increased LIF expression in tumors." (PMID 26716902, 2016). "Together, these results strongly suggest that LIF promotes EMT of cancer cells through the induction of miR-21." (PMID 26716902, 2016). "Together, these results strongly suggest that LIF upregulates miR-21 through the STAT3 signaling pathway to promote EMT in cancer cells." (PMID 26716902, 2016). "LIF overexpression increases the proliferation rate of in vitro cultured cancer cells, the growth rate of xenograft tumors and metastasis of many different types of human tumors." (PMID 26716902, 2016). "Pro-inflammatory cytokine LIF is secreted by cancer cells and fibroblasts treated with TGF-β1, which highlights the action of TGF-β1 as a driver of tumor-associated inflammation." (PMID 25853091, 2015). "The proinflammatory cytokine LIF reprograms fibroblasts into a proinvasive phenotype, which promotes extracellular matrix remodelling and collective invasion of cancer cells." (PMID 26667266, 2015). "Overall, our results indicate that LIF signaling in CCA is a mechanism that promotes cancer growth and progression." (PMID 26296968, 2015). "Leukemia inhibitory factor (LIF), an IL-6 family cytokine, promotes progression of various carcinomas." (PMID 26296968, 2015). "Meanwhile, LIF has also been reported to induce the differentiation of murine myeloid leukemia cells and inhibit proliferation and growth in some other cancer cell lines." (PMID 24553191, 2014). "Limited studies suggested the potential complex role of LIF in cancer depending upon the types of the cancer." (PMID 24553191, 2014). "The pair-wise comparison also revealed that 5/23 of the abnormal cases (4 metaplasia and 1 carcinoma) had a LIF response detectable by the activation of ERK and STAT3." (PMID 16271139, 2005). "In PDAC mouse models, a CAF-to-myoCAF could be mediated by IL-33-ST2-MYC-CXCL3-CXCR2 axis or JAK/STAT signaling activated by macrophage-derived progranulin and cancer cell-secreted leukemia inhibitory factor (LIF)." (PMID 40380196, 2025). "However, in pathological conditions such as cancer cachexia, LIF production becomes chronic, dysregulated, and systemic." (PMID 40869331, 2025). "We next explored the disease relevance of cancer cell-derived LIF and Gal3 signaling to the brain." (PMID 38467743, 2024). "Partial suppression of a pSTAT3+myMAF phenotype by neutralisation of LIF from cancer cell CM suggested that other cancer cell-derived factors may also play a role." (PMID 38678021, 2024). "Moreover, by reducing HB-EGF expression in cancer cells and then co-culturing the cells with CAFs, we also observed strong downregulation of both LIF and CSF2 expression." (PMID 39262776, 2024). "LIF is frequently overexpressed in solid tumors, correlating with poor cancer patient prognosis." (PMID 38245529, 2024). "An autocrine or paracrine loop of LIF/LIFR has been shown in different types of cancer." (PMID 38789520, 2024). "Moreover, through the multi-omic screening, we successfully identified LIF and Gal3 as the key cytokines released by those cancer cells that robustly trigger neural activities in specific brain regions." (PMID 38467743, 2024). "Targeting LIF/LIFR might avoid side effects linked to pan-FGFRs inhibitor and might be a promising therapeutic strategy for the treatment of cancers with aberrant FGFR4 activation." (PMID 37945798, 2024).
cancer (continued). "In addition, LRI-201 treatment also reversed the increment of MUC2 mRNA expression induced by LIF suggesting a potential role of the axis LIF/LIFR/FGFR4 in the onset of cancer." (PMID 37945798, 2024). "We further tested LIF KO or Gal3 KO cancer cells in Th-Cre;TrkAfl/fl and control littermates." (PMID 38467743, 2024). "This phenomenon raised the challenging issue that additional cancer cell-derived factor(s) might exist to function cooperatively with LIF in neural activation." (PMID 38467743, 2024). "Because cancer cell-derived LIF and Gal3 cooperatively activated the PVN, a central brain region that controls efferent sympathetic action, we explored whether local sympathetic inputs in specific lymphoid organs might modulate MDSC generation." (PMID 38467743, 2024). "There are multiple mechanisms that converge on FGFR4 regulation, and in addition to the direct induction caused by H. pylori protein acting on cancer epithelial cells, we have now revealed a regulatory network supported by both FGF19, the natural ligand of FGFR4, and by LIF/LIFR." (PMID 37945798, 2024). "Clinically, increased LIF abundance in clinical samples correlate with malignant clinicopathological features and patient prognosis; higher LIF concentrations in presurgical plasma dramatically diminish following cancer eradication." (PMID 39206755, 2024). "Recently, other cytokines have been described as being involved in the pathophysiological mechanism of cancer cachexia: TNF receptor (TNFR)-associated factor 6 (TRAF6), TNF-like inducer of apoptosis (TWEAK), leukemia inhibitory factor (LIF), and interferon-gamma (IFN-γ)." (PMID 38067294, 2023). "Collectively, we propose the parallel mechanisms of IL-1α and LIF that can synergize to activate splenic HSC niche to increase PMN production that may function in human cancers." (PMID 37134077, 2023). "Although increasing numbers of studies have investigated the expression and functions of LIF within various cancers, there are still have limitation of clinical trials that explore a therapeutic agents aimed at affecting LIF signaling for improving outcomes for patients with cancers." (PMID 36925915, 2023). "LIF is a pleiotropic member of interleukin (IL)-6 cytokine family, that regulates cell differentiation, proliferation and survival in embryo and adult cells and is involved in cancer growth and progression." (PMID 36998446, 2023). "We tested whether LIF might have a role in cancer-induced EMH by generating a lentiviral expression vector for murine LIF and injecting mice intravenously to induce systemic LIF overexpression." (PMID 37134077, 2023). "The aim of this study was to investigate the potential of conditioned media from cancer stem cells to modulate the fate of Leukemia Inhibitory Factor (LIF)-dependent murine embryonic stem cells (mESCs) as a way to obtain a direct readout of the secretome of cancer cells." (PMID 38137514, 2023). "Taken together, our results indicated that cancer-associated regulatory hubs could represent intrinsic characteristics of each stage of CRC and LIF–LIFR interaction was discovered to be screwed in advanced CRC." (PMID 37360193, 2023). "Subsequent study further found refunctionalizing of another pseudogene, LIF, may mediate the cancer resistance and body size in elephants." (PMID 37395176, 2023). "Besides chemokines of NF-κB signaling, the inflammatory cytokines TNF-α and LIF were highlighted to play a role in interaction with CXCL-8 in cancer development and the chemokines CXCL3 and CXCR2 in their role in cell migration." (PMID 37048115, 2023). "It will be interesting to elucidate whether LIF plays a similar role in glucose metabolic rewiring in those cancer types, which in turn contributes to tumorigenesis." (PMID 35440095, 2022).
cancer (continued). "Since previous studies have shown that challenging cancer cells with LIF promotes their proliferation and the epithelial-to-mesenchymal transition (EMT), we functionally assessed whether LIFR inhibition reverses this pattern." (PMID 36359879, 2022). "We first examined whether an allosteric Shp2 inhibitor (RMC-4550: iShp2), which was initially developed to decouple the oncogenic Ras-to-Erk signaling in human cancers, inhibits LIF-dependent Erk activation." (PMID 35850773, 2022). "LIF has been or is being extensively studied within breast, hematopoietic, and pancreatic cancers." (PMID 35204717, 2022). "The analysis of metabolite pool size in cancer cells showed that LIF drove glucose metabolic reprogramming; ectopic LIF expression increased the levels of intermediates of glycolysis, including 3-phosphoglycerate (3-PG), phosphoenol pyruvate (PEP), and lactate." (PMID 35440095, 2022). "This review will summarize current knowledge of how LIF expression impacts cellular function and dysfunction to help reveal new adjuvant treatment options for cancer patients, while also revealing potential adverse effects of treatments targeting LIF signaling." (PMID 35204717, 2022). "Next, we investigated the effect of treatment by the small molecule inhibitors EC330 (a small molecule compound that effectively inhibits the function of LIF in promoting the proliferation and migration of cancer cells 31) and SB225002 (targeting CXCR2) on lung metastasis." (PMID 35280694, 2022). "Different sources of LIF have different effects on cancer cells." (PMID 35280694, 2022). "Fully understanding the effects of LIF signaling within cancers and within the body as a whole offers potentials for improved cancer screening tests, cancer monitoring, and cancer treatment, as well as avenues for treatment of various other pathological processes." (PMID 35204717, 2022). "LIFR and its major ligand LIF belong to the interleukin-6 (IL-6) cytokine family and have a central role in immune system regulation, carcinogenesis, and dissemination in several human cancers." (PMID 35847866, 2022). "Cancer cells have also developed ways to evade recognition and destruction by immune cells, and LIF may contribute to this." (PMID 35204717, 2022). "In the female reproductive system, LIF expression is necessary for blastocyst invasion into the endometrium and implantation, which supports research showing the capabilities of LIF to contribute to invasiveness of cancer cells." (PMID 35204717, 2022). "LIF is elevated in patient plasma in many different cancer types, and, therefore, it has potential as a non-specific cancer biomarker (although studies are needed to determine plasma levels of LIF in patients with non-cancer pathologies in addition to the healthy control subjects typically used)." (PMID 35204717, 2022). "Therefore, LIF has been believed to have a potential role in promoting dedifferentiation and self-renewal of cancer stem cells (CSCs)." (PMID 35204717, 2022). "It has been shown that numerous cancers, including pancreatic, colorectal, esophageal, ovarian, renal, gastric, uterine squamous, and testicular cancers, could aberrantly highly express LIF." (PMID 35740622, 2022). "The various roles of LIF within various cancers highlight its potential as a target for adjuvant treatments, but its broad physiological roles must also be kept in mind, as disrupting LIF signaling could potentially cause a multitude of adverse effects." (PMID 35204717, 2022). "Additionally, CAFs secrete paracrine factors, that act as STAT3 activators on cancer cells, of which, leukemia inhibitory factor (LIF) is a key player." (PMID 35565450, 2022).